TRIM66 (tripartite motif containing 66)
Description:
May function as transcription repressor; The repressive effects are mediated, at least in part, by recruitment of deacetylase activity. May play a role as negative regulator of postmeiotic genes acting through CBX3 complex formation and centromere association (By similarity).
Synonyms: C11orf29; KIAA0298; TIF1D; TIF1DELTA
Target class: Epigenetic regulator; Bromodomain; Reader
Gene: Protein-coding gene on chromosome 11 (8,612,037 to 8,682,694, reverse strand). Ensembl gene ENSG00000166436.
Subcellular location: Nucleus
Subcellular location (Human Protein Atlas): Nucleoplasm
Genetic constraint (gnomAD): Loss-of-function variants: 92 observed, 148.34 expected, observed/expected ratio (o/e) 0.62, 90% interval 0.52 to 0.74. The upper end of that interval is the gene's LOEUF score, 0.74, which puts it in group 3 of 6, group 1 being the genes least tolerant of losing a copy. Missense variants: 1,629 observed, 1,727.4 expected, observed/expected ratio (o/e) 0.94, 90% interval 0.9 to 0.98. Synonymous variants: 602 observed, 644.15 expected, observed/expected ratio (o/e) 0.93, 90% interval 0.87 to 1.
Homologues: Orthologues: macaque TRIM66 (95% identical), chimpanzee TRIM66 (89% identical), dog TRIM66 (84% identical), guinea pig TRIM66 (81% identical), mouse Trim66 (81% identical), rat Trim66 (81% identical), rabbit TRIM66 (80% identical), pig TRIM66 (67% identical), zebrafish trim66 (23% identical). Paralogues in human: TRIM33 (22% identical), TRIM24 (21% identical), TRIM28 (13% identical), TRIM2 (9% identical), TRIM3 (8% identical), TRIM37 (8% identical), TRIM71 (8% identical), TRIM9 (7% identical), TRIM46 (7% identical), PML (7% identical), TRIM67 (7% identical), MID1 (7% identical), and 68 more.
Diseases named in the same sentence as TRIM66 in open-access papers:
TRIM66 is named in the same sentence as 23 diseases in open-access papers, as found by Europe PMC text mining. Sharing a sentence is not in itself a finding about the gene and the disease. The quoted sentences say what the papers report.
osteosarcoma (7 papers, 2015 to 2024). A usually aggressive malignant bone-forming mesenchymal neoplasm, predominantly affecting adolescents and young adults. "TRIM66 mRNA is abnormally upregulated in osteosarcoma tissues, and its high expression is closely associated with local recurrence, lung metastasis, and low survival rates in osteosarcoma patients." (PMID 39062505, 2024). "TRIM66 expression was higher in osteosarcoma tissues than normal healthy tissue and was associated with poorer survival." (PMID 32731534, 2020). "In the current study, we reported a significant elevation of TRIM66 in osteosarcoma tissues and its high expression was associated with poor prognosis of this disease." (PMID 26247633, 2015). "Further clinical characteristics analysis showed that high expression level of TRIM66 was associated with local recurrence, lung metastasis and poor survival rate in patients with osteosarcoma." (PMID 26247633, 2015). "Then we examined the association of TRIM66 and osteosarcoma by knockdown its expression in two osteosarcoma cell lines." (PMID 26247633, 2015). "As TRIM66 expression level associated with patients’ survival rate, TRIM66 might be a useful prognostic factor for osteosarcoma." (PMID 26247633, 2015). "Knockout of the TRIM66 gene inhibits the proliferation, migration, and cell cycle progression of osteosarcoma cells, but induces apoptosis." (PMID 39062505, 2024). "Precisely, TRIM66 was identified as an oncogenic factor in glioma, osteosarcoma, lung, liver, and prostate tumors." (PMID 36674511, 2023). "We then estimated TRIM66 expression in five osteosarcoma cell lines, U-20S, Saos2, Sw1353, MG63 and HOS, by real-time PCR and Western blot." (PMID 26247633, 2015). "In the current study, we explored the expression and biological functions of TRIM66 in osteosarcoma and sought to identify the involved mechanisms." (PMID 26247633, 2015). "This study was aimed at elucidating the expression and biological function of TRIM66 in osteosarcoma." (PMID 26247633, 2015). "We found that the mRNA level of TRIM66 was significantly increased in osteosarcoma tissues compared to bone cysts tissues." (PMID 26247633, 2015). "Further, our immunohistochemistry results also demonstrated an increase of TRIM66 protein in 63.4% of osteosarcoma tissues." (PMID 26247633, 2015). "Our data suggested TRIM66 was significantly overexpressed in osteosarcoma tissues compared with that in bone cysts (P < 0.05), which was consistent with the analysis on data from GEO dataset (Access ID: GSE3628) (P < 0.05)." (PMID 26247633, 2015). "TRIM66-siRNA was able to efficiently suppress endogenous TRIM66 expression in osteosarcoma cells, whereas TRIM66 expression remained unaffected in NC-transfected cells." (PMID 26247633, 2015). "Then, we further investigated the TRIM66 protein expression in osteosarcoma and bone cysts by immunohistochemistry." (PMID 26247633, 2015). "Firstly, our study identified TRIM66 as a useful biomarker for the diagnosis and prognosis of osteosarcoma." (PMID 26247633, 2015). "Here, we found that knockdown of TRIM66 significantly impaired cell growth and cell cycle progression in osteosarcoma." (PMID 26247633, 2015). "Collectively, our data suggest that TRIM66 is a potent prognostic factor of osteosarcoma and TRIM66 plays a critical role in osteosarcoma carcinogenesis." (PMID 26247633, 2015). "To investigate the TRIM66 expression in osteosarcoma, we first detected its mRNA levels in 45 osteosarcoma tissues and 14 bone cysts by real-time PCR." (PMID 26247633, 2015). "Then, we found that knockdown of TRIM66 in two osteosarcoma cell lines, MG63 and HOS, significantly inhibited cell proliferation and induced G1-phase arrest." (PMID 26247633, 2015).
osteosarcoma (continued). "The in vitro experiments showed that silencing of TRIM66 expression in osteosarcoma cells inhibited cell growth, metastasis and tumorigenicity in nude mice, while induced cell apoptosis." (PMID 26247633, 2015). "We then explored the effects of TRIM66 in the apoptosis of osteosarcoma cells by Annexin V-FITC/PI staining assay." (PMID 26247633, 2015). "Our own real-time PCR results and analysis on an independent dataset demonstrated that TRIM66 mRNA level was higher in osteosarcoma tissues as comparing to bone cysts or normal bone tissues." (PMID 26247633, 2015). "Then we assessed whether TRIM66 affects the cell cycle of osteosarcoma cells by PI staining and flow cytometry analysis." (PMID 26247633, 2015). "To investigate whether TRIM66 overexpression correlates with osteosarcoma prognosis, we analyzed the correlations between clinicopathological characteristics and the protein expression of TRIM66 in 101 patients with osteosarcoma by Chi-square test." (PMID 26247633, 2015). "The inhibitory effects of SB431542 on cell invasion in osteosarcoma cells was weakened by TRIM66 overexpression, which suggested TRIM66 may promote cell invasion partially by activating TGF-β pathway." (PMID 26247633, 2015). "Then we explored the role of TRIM66 in osteosarcoma cells by RNA interference." (PMID 26247633, 2015). "Here, TRIM66 expression level was higher in osteosarcoma tissues than in normal tissues." (PMID 26247633, 2015). "Moreover, inhibition of TRIM66 in osteosarcoma cells significantly induced cell apoptosis, while remarkably inhibited cell migration, invasion as well as tumorigenicity in nude mice." (PMID 26247633, 2015). "Our data suggested that TRIM66 siRNA may inhibit osteosarcoma cell invasion through suppressing EMT." (PMID 26247633, 2015). "Then, we investigated whether TRIM66 affected the migrated and invasive ability of osteosarcoma cells." (PMID 26247633, 2015). "Further, the inhibitory effects of TGF-β inhibitor, SB431542 on cell invasion in osteosarcoma cells was weakened by TRIM66 overexpression, which suggested TRIM66 may promote cell invasion partially by activating TGF-β pathway." (PMID 26247633, 2015). "TRIM66 may be a prognostic factor and potential therapeutic target in osteosarcoma." (PMID 26247633, 2015). "The exact pathway that TRIM66 may regulate in osteosarcoma remains unclear." (PMID 26247633, 2015). "Further, we performed GSEA on E-MEXP-3628 dataset and identify that TRIM66 expression was positively correlated with several cancer-related networks, including apoptosis, EMT and TGF-β pathway, which was then confirmed in osteosarcoma cells by Western blot." (PMID 26247633, 2015). "In conclusion, TRIM66 may act as an oncogene through suppressing apoptosis pathway and promoting TGF-β signaling in osteosarcoma carcinogenesis." (PMID 26247633, 2015).
prostate carcinoma (6 papers, 2020 to 2025). A carcinoma that arises from epithelial cells of the prostate gland. "We then established TRIM66‐deficient cells derived from two independent prostate cancer cell lines, PC‐3 and DU145." (PMID 31981447, 2020). "Our previous study unambiguously underlined the importance of TRIM66 in prostate cancer cells with previously unacknowledged molecular mechanisms." (PMID 31981447, 2020). "TRIM66 deficiency inhibited migration and invasion of prostate cancer cells." (PMID 31981447, 2020). "Notably, despite the uncovered TRIM66–STAT2–IL‐2 prostate cancer, the molecular mechanisms underlying TRIM66‐mediated STAT2 regulation were still obscure, which warrants further investigations." (PMID 31981447, 2020). "Furthermore, TRIM66 deficiency inhibited migration and invasion of prostate cancer cells." (PMID 31981447, 2020). "We previously evidenced that TRIM66 promoted malignant behaviors of prostate cancer cells, including proliferation, migration, and invasion." (PMID 34613933, 2021). "Our group previously found that Chinese medicine Zhoushi Qi Ling decoction suppressed the development of prostate cancer by negatively regulating TRIM66/HP1γ/AR axis." (PMID 34613933, 2021). "Next, we sought to clarify the potential influence of TRIM66 silencing on the migrative and invasive capacities of prostate cancer cells." (PMID 31981447, 2020). "Despite the well‐recognized roles of TRIM66 in an array of human cancers, the expression status and mechanistic involvement of TRIM66 in prostate cancer were still elusive." (PMID 31981447, 2020). "Consistent with the recognized oncogenic properties of JAK/STAT signaling, here we demonstrated that this pathway was abnormally activated by TRIM66 in prostate cancer cells." (PMID 31981447, 2020). "Our study highlights the importance of the TRIM66–signal transducer and activator of transcription 2–interleukin‐2 signaling axis in the tumor biology of prostate cancer." (PMID 31981447, 2020). "Our data clearly indicated that TRIM66 indispensably contributed to the EMT processing in prostate cancer cells." (PMID 31981447, 2020). "In view of the complex regulatory network downstream of JAK/STAT signaling, we sought to further characterize the critical target molecule modulated indirectly by TRIM66 in prostate cancer cells." (PMID 31981447, 2020). "Here we set out to address this issue and characterize the importance of TRIM66 in proliferation, cell cycle, migration and invasion of prostate cancer cells." (PMID 31981447, 2020). "In summary, here we have demonstrated the oncogenic role of TRIM66 in prostate cancer cells via positive regulation of JAK/STAT signaling, which holds great promise for therapeutic exploitations." (PMID 31981447, 2020). "Here we initiated the establishment of TRIM66‐silenced prostate cancer cells and determined their influence on malignant behaviors, such as cell viability, proliferation, migration and invasion." (PMID 31981447, 2020). "The data acquired in STAT2‐deficient PC‐3 cells almost completely recapitulated the antitumor phenotypes elicited by TRIM66 knockdown, which implicated the important role of STAT2 in mediating the oncogenic activities of TRIM66 in prostate cancer cells." (PMID 31981447, 2020). "TRIM66 promotes the malignant biological behavior of prostate cancer through JAK/STAT pathway." (PMID 37600786, 2023). "However, the possible involvement and potential mechanistic contribution of TRIM66 in prostate cancer are currently elusive and yet to be comprehensively defined." (PMID 31981447, 2020). "Therefore, our data suggested the oncogenic properties of TRIM66 in prostate cancer cells and TRIM66 knockdown greatly suppressed cell malignant proliferation in vitro." (PMID 31981447, 2020).
prostate carcinoma (continued). "In view of recognized oncogenic properties of TRIM66 in a number of human cancers, here we initially analyzed relative abundance of TRIM66 in clinical prostate tumor samples and found significant up‐regulation of TRIM66 in prostate cancer in comparison with normal control." (PMID 31981447, 2020). "Notably, our results further uncovered the oncogenic activities of IL‐2 in prostate cancer cells, wherein IL‐2 was subjected to TRIM66‐positive regulation, and IL‐2 silencing greatly compromised cell proliferation, invasion and migration." (PMID 31981447, 2020). "Here, we investigated the potential oncogenic properties of TRIM66 in prostate cancer." (PMID 31981447, 2020). "In view of the assembly of evidences uncovering aberrances of JAK/STAT signaling in multiple forms of human cancers, here we focused on the potential linkage between TRIM66 and the JAK/STAT pathway in prostate cancer." (PMID 31981447, 2020). "Tripartite Motif Containing 66 (TRIM66) knockdown suppressed viability and proliferation of prostate cancer cell lines." (PMID 31981447, 2020). "Our data suggested that IL‐2 was subjected to TRIM66/JAK/STAT regulation, which eventually contributed to the malignant growth and metastasis of prostate cancer cells." (PMID 31981447, 2020). "We report that shRNA‐mediated knockdown of TRIM66 significantly suppressed viability and proliferation of both PC‐3 and DU145 prostate cancer cell lines." (PMID 31981447, 2020). "Interestingly, another study revealed that TRIM66 promotes the malignant progression of prostate carcinoma through the JAK/STAT pathway, highlighting its importance in the proliferation, cell cycle regulation, migration, and invasion of prostate cancer cells." (PMID 39160596, 2024).
non-small cell lung carcinoma (4 papers, 2015 to 2022). A group of at least three distinct histological types of lung cancer, including non-small cell squamous cell carcinoma, adenocarcinoma, and large cell carcinoma. "For example, knockdown of TRIM66 inhibited malignant behavior and epithelial–mesenchymal transition in non-small-cell lung cancer, suggesting that TRIM66 was an oncogene that promoted lung cancer progression." (PMID 30837324, 2019). "TRIM66 was also highly expressed in non-small cell lung carcinoma (NSCLC) and its expression correlated with metastasis." (PMID 32731534, 2020).
glioma (2 papers, 2022 to 2023). A benign or malignant brain and spinal cord tumor that arises from glial cells (astrocytes, oligodendrocytes, ependymal cells). "Mechanistically, TRIM66-induced upregulation of GLUT3 protein was shown to be a result of the binding of c-MYC on SLC2A3/GLUT3 promoters in glioma cells." (PMID 36139694, 2022). "This shows that TRIM66 can exert an oncogenic potential since in vitro and in vivo assays showed that TRIM66 induces glioma cell proliferation, migration, and tumor growth." (PMID 36139694, 2022). "In addition, TRIM66 appears to regulate the metabolic potential of glioma cells, since its expression affected ATP levels and glucose uptake." (PMID 36139694, 2022).
prostate tumor (2 papers, 2020 to 2023). "Again, a slightly but significantly positive correlation between TRIM66 and IL‐2 was observed in the clinical prostate tumor database (P < 0.01), which was consolidated by the down‐regulation of IL‐2 at both transcript and protein levels in TRIM66‐deficient PC‐3 cells." (PMID 31981447, 2020). "In prostate tumors, TRIM66 promotes malignant progression through the JAK/STAT signaling pathway." (PMID 36674511, 2023).
sarcoma (2 papers, 2021). A usually aggressive malignant neoplasm of the soft tissue or bone. "A higher expression of TRIM66 is significantly associated with worse survival for KIRC patients and better survival for Sarcoma (SARC), Head and Neck Squamous Cell Carcinoma (HNSC), and Pancreatic Adenocarcinoma (PAAD) patients." (PMID 33810347, 2021).
bladder cancer (1 paper, 2025). "Fourteen TRIM family proteins were associated with bladder cancer (tumor-promoting: TRIM9, TRIM25, TRIM26, TRIM28, TRIM29, TRIM59, TRIM65, and TRIM66; tumor-suppressive: TRIM19 and TRIM38)." (PMID 40723250, 2025). "Other TRIM proteins (TRIM9, TRIM38, TRIM65, and TRIM66) promoted progression of bladder cancer by targeting GLUT1, ANXA2, and MMP11." (PMID 40723250, 2025).
gastric cancer (1 paper, 2022). A primary or metastatic malignant neoplasm involving the stomach. "TRIM66 expression has been shown to promote malignant progression in several types of cancer, including HCC, and MCTP2 inhibited cisplatin resistance in gastric cancer." (PMID 36035299, 2022).
glaucoma (1 paper, 2021). Increased pressure in the eyeball due to obstruction of the outflow of aqueous humor. "We investigated the association of the single nucleotide polymorphism (SNP) rs112369934 near the TRIM66 gene with qualitative and quantitative phenotypes of primary open-angle glaucoma (POAG) in African Americans (AA)." (PMID 34573402, 2021). "In mouse models, the differential expression patterns of TRIM66 indicated an important role in glaucoma pathogenesis and progression to later stages of the disease." (PMID 34573402, 2021).
liver cancer (1 paper, 2020). An epithelial or non-epithelial malignant neoplasm that arises from the liver. "TRIM66 promotes malignant progression of liver cancer by inhibiting E-cad expression through the EMT pathway." (PMID 31988090, 2020).
melanoma (1 paper, 2020). A malignant, usually aggressive tumor composed of atypical, neoplastic melanocytes. "To identify whether TRIM24HIGH, TRIM33HIGH, or TRIM66HIGH melanoma phenotype reflected the one observed in TRIM28HIGH expressing melanomas, we searched for genes that correlate with the expression of TRIM24, TRIM33, TRIM66, and TRIM28 in SKCM TCGA data." (PMID 33076560, 2020). "Interestingly, the expression of other close-related TRIM family members’ (namely, TRIM24, TRIM33, and TRIM66) does not correlate with the survival of melanoma patients, suggesting that TRIM28 is specifically involved in melanoma progression." (PMID 33076560, 2020).
metastasis (1 paper, 2015). The spread or migration of cancer cells from one part of the body (where they first appeared) to another. "High TRIM66 expression was correlated with high rate of local recurrence and lung metastasis, and short survival time." (PMID 26247633, 2015).
Obesity (1 paper, 2024). Accumulation of substantial excess body fat. "Furthermore, genome-wide association studies (GWAS) have identified TRIM66 as a potential gene influencing the metabolism and obesity (NHGRI-EBI GWAS database)." (PMID 38719749, 2024).